EGFR (epidermal growth factor receptor)
Diseases named in the same sentence as EGFR in open-access papers (continued):
Sharing a sentence is not in itself a finding about the gene and the disease.
lung cancer (continued). "The knockdown of ANXA1 increased chemosensitivity to Osimertinib and decreased tumorigenesis, invasion and migration of lung cancer cells with EGFR mutations." (PMID 34439260, 2021). "A better understanding of the risk factors for EGFR mutation-positive lung cancer will be required to identify its causes and to develop public health strategies for its prevention and early detection." (PMID 33961689, 2021). "As reported, a second point mutation happens in the DNA sequence of the EGFR gene in patients with non–small-cell lung cancer at relapse due to the obvious gefitinib resistance." (PMID 34322025, 2021). "Epidermal growth factor receptor (EGFR) tyrosine kinase inhibitors (TKIs) are first-line drugs for lung cancers with activating EGFR mutations." (PMID 33572269, 2021). "The most successful example is the identification of activating mutations of the EGFR gene in patients with non–small cell lung cancer (NSCLC) for the administration of EGFR-kinase–targeting drugs." (PMID 34559836, 2021). "They established a gefitinib-resistant cell line model with MET gene amplification by exposing a gefitinib-sensitive lung cancer cell line (HCC827) with an activating EGFR mutation (exon 19 E746_A750 del) to increasing concentrations of gefitinib." (PMID 33572269, 2021). "The patient underwent an EGFR gene testing of the primary lung cancer which harbored a 19th exon mutation." (PMID 33975638, 2021). "Our previous study showed that overexpression of Nrf2 due to Keap1 mutation increased cell invasion and metastatic ability of EGFR tyrosine kinase inhibitor (TKI)-resistant lung cancer cells both in vitro and in vivo." (PMID 33441941, 2021). "Epidermal growth factor receptor (EGFR) exon 20 insertion mutations account for a tenth of all EGFR mutations in lung cancers." (PMID 34944068, 2021). "As lung cancer patients harbouring EGFR mutations would benefit from EGFR inhibition and the expression of PD-L1 allows for treatment with immune checkpoints blockades such as PD-1/PD-L1 inhibitors." (PMID 33956842, 2021). "The epidermal growth factor receptor (EGFR) gene of the primary lung cancer harbored a mutation of the 19th exon." (PMID 33975638, 2021). "In the final analysis cohort, a total of 22 germline EGFR variants were identified in 64 patients with lung cancer." (PMID 34869019, 2021). "We found that the 2-undecen-4-ol (FC = 1.51, p value = 0.01), 2H-tetrazole, 2-methyl- (FC = 1.37, p value = 0.03), 2-propanol, 1-chloro-3-propoxy- (FC = 1.47, p value = 0.04) were significantly increased in the lung cancer subjects with EGFR mutation." (PMID 34193905, 2021). "In EGFR mutation-positive lung cancers, exon 19 deletion mutation and exon 21 L858R point mutation, among others, cause the kinase to become homeostatically activated in a ligand-independent manner." (PMID 34831415, 2021). "The discovery of epidermal growth factor receptor (EGFR) oncogenic driver mutations preluded a new therapeutic area for lung cancer treatment in the past decade." (PMID 34809713, 2021). "A well-known pair of genes that validates our mutual exclusion data is KRAS with mutated EGFR loci, most commonly seen in lung cancer." (PMID 34204917, 2021). "In HCC827, a lung cancer cell line with EGFR mutation, RESV either alone or in combination with PRI-2191 did not affect the level of VEGF secreted by the cells." (PMID 33652978, 2021). "It has been reported that the EGFR mutation rate is 30–40% in Asian lung cancer patients and 10–15% in European Caucasian patients." (PMID 34217313, 2021). "Although smoking has been well established as the major cause of lung cancer, EGFR mutations have proved to be the most common genetic alteration in never-smoking NSCLC patients." (PMID 34422624, 2021). "In the current study, our data revealed 98 (56.7%) EGFR mutations in 173 patients with lung cancer and 14 (2.7%) ALK fusions in 521 patients." (PMID 34234236, 2021).
lung cancer (continued). "At present, there are approved drugs for lung cancer, targeting tumor cells with mutated EGFR, ALK and ROS1 fusions, and mutated BRAF." (PMID 34217228, 2021). "Our group has recently profiled a large Nova Scotian lung cancer patient cohort for major driver mutations in lung cancer (EGFR, ALK, KRAS, BRAF, and PIK3CA)." (PMID 33956842, 2021). "Although epidermal growth factor receptor (EGFR) mutations are a good prognostic factor in resected lung cancer, many patients with early resected EGFR-mutated lung cancer experience recurrence." (PMID 34298845, 2021). "The more complex genomic mutation features in patients with SCC often result in a failure to benefit from EGFR mutation based molecular targeted lung cancer therapy." (PMID 34459571, 2021). "The population-based incidence rates provide a more complete assessment of the risk of EGFR mutation-positive lung cancer than do the EGFR mutation-positive proportions." (PMID 33961689, 2021). "A total of 22 germline EGFR variants were identified in 64 patients with lung cancer, accounting for 0.2% of the total cases studied." (PMID 34869019, 2021). "Osimertinib (EGFR TKI) is used to treat patients with EGFR-mutated lung cancer and as observed for other TKIs, some patients demonstrated intrinsic resistance with insufficient response to the drug." (PMID 33806258, 2021). "Another study reported that the response rate for osimertinib is relatively low (66.7%) in patients whose lung cancer has an EGFR mutation and a high AXL expression (IHC score 3+)." (PMID 33572269, 2021). "Most of the results were obtained in lung cancer models because EGFR is often mutated in this cancer type." (PMID 34503236, 2021). "Recently, much progress has been made toward advancing lung cancer treatments, such as EGFR mutation-based targeted therapies." (PMID 33787673, 2021). "Numerous studies on the molecular mechanisms of drug tolerance of EGFR-mutated lung cancers employ lung cancer cell lines as models." (PMID 34202566, 2021). "EGFR-mutated lung cancer is reported to comprise approximately 45% of the NSCLC cases in Asia and approximately 15% in Europe and the United States." (PMID 33757469, 2021). "In this review, the function of exosomes in lung cancer is discussed, with a specific focus on lung cancers harboring EGFR mutations." (PMID 33855679, 2021). "Numerous intracellular molecules are also candidate inducers of drug tolerance in EGFR-mutated lung cancers." (PMID 34202566, 2021). "A homozygous deletion mutation of CDKN2A (P16) was found in 31 patients with 127 EGFR mutations in lung cancer treated with EGFR-TKIs." (PMID 35004697, 2021). "Henning Willers and colleagues found that PARP inhibitor by controlling ROS levels upon EGFR TKI treatment, promoted the sensitivity of EGFR-mutated lung cancer to tyrosine kinase inhibitor treatment." (PMID 34285141, 2021). "Clinical research data show that gefitinib greatly improves the progression‐free survival of patients, so it is used in advanced non‐small cell lung cancer patients with EGFR mutation." (PMID 33491264, 2021). "Based on the positive results of the AURA3 study, osimertinib was first approved for the treatment of patients with EGFR T790M mutation‐positive non‐small cell lung cancer (NSCLC) in progression after EGFR‐TKI therapy." (PMID 33939301, 2021). "Quercetin inhibited tumor growth to a similar extent to brigatinib, a drug known to overcome AZD9291 resistance associated with EGFR C797S in lung cancer." (PMID 34572484, 2021). "Subtypes of lung cancer were also identified: EGFR mutations were identified with 87% accuracy, MET amplification with 91% accuracy, and KRAS mutations with 90% accuracy." (PMID 34873529, 2021). "Two studies have presented detailed micro-costing of ctDNA-based hotspot panels to detect either KRAS or EGFR mutations for the treatment of colorectal or lung cancer." (PMID 33440749, 2021).
lung cancer (continued). "Despite the introduction of epidermal growth factor receptor (EGFR) tyrosine kinase inhibitors (TKIs) to treat advanced lung cancer harboring EGFR-activating mutations, the prognosis remains unfavorable because of intrinsic and/or acquired resistance." (PMID 34298655, 2021). "On the contrary, the population-based incidence rates showed that Māori had approximately two times increased risk, and Pacifica and Asians had approximately 3.5 times increased risk for EGFR mutation-positive lung cancer compared with New Zealand Europeans." (PMID 33961689, 2021). "In this study, we found that mutations of the EGFR gene in exons E18, E19, and E20 in lung cancer patients were common in adenosquamous carcinoma, while E21 mutations were common in adenocarcinoma." (PMID 34217313, 2021). "Owing to the low prevalence of EGFR germline mutations in lung cancer patients, this study is a retrospective descriptive study." (PMID 34869019, 2021). "For example, microtubule inhibition caused inactivation of the EGFR receptor in specific cancer types and caused resensitization of resistant lung cancer cell lines to EGFR inhibitors, suggesting a synergistic effect for both drugs." (PMID 34832895, 2021). "Rac1 inhibition reduces COLI uptake in mutated lung cancer cells (PC-9) and restores their sensitivity to EGFR-TKI." (PMID 34976811, 2021). "Fortunately, some mutations in the EGFR gene in lung cancer cells bring patients the opportunity to receive targeted therapy and improve their prognosis." (PMID 33875644, 2021). "Although the results of these studies are not conclusive, some of them show an association between EGFR SNPs and the efficacy of EGFR–targeted treatment in lung cancer as well as in other solid tumors." (PMID 34070597, 2021). "The aim of our systematic review is to gain more insight in reporting of bone metastases, skeletal-related events, and bone-specific outcome of treatment in clinical trials enrolling patients with EGFR-mutated lung cancer." (PMID 34201833, 2021). "The development of resistance to EGFR tyrosine kinase inhibitors (TKIs) is still a critical problem in lung cancer, and the underlying mechanisms remain fully unexplored." (PMID 34976811, 2021). "EGFR mutations play important roles in the development and treatment of lung cancer, and they occur frequently in Taiwanese people and other Asians." (PMID 33809651, 2021). "Somatic mutations in EGFR occur in around 15–30% of lung adenocarcinomas (LUADs), the major subtype of lung cancer." (PMID 34944063, 2021). "Among more than 300 mutations in lung cancer, only a few of these genes such as EGFR, ALK, c-met, ROS1can promote or drive the lung tumorigenesis." (PMID 33504342, 2021). "EGFR’s aberrant expression and activation is associated with various types of cancer, including lung cancer." (PMID 34684727, 2021). "Epidermal growth factor receptor (EGFR), one of the most potent oncogenes that is frequently mutated and highly expressed in a variety of human cancers (e.g., lung cancer and glioblastoma), was selected as the siRNA target." (PMID 33782530, 2021). "In particular, the epidermal growth factor receptor (EGFR) is one of the most frequently mutated oncogenes in lung cancer and other cancer types." (PMID 34610265, 2021). "Activation of YAP and FOXM1 axis induced EMT-associated EGFR-TKI resistance in lung cancer by dysregulating mitosis." (PMID 34322664, 2021). "A comparison with the Cobas EGFR Mutation Test v2 was performed using reference materials and plasma from lung cancer patients." (PMID 34199654, 2021). "Molecular structural analysis, dynamics simulations and computational characterization have facilitated a great number of studies of EGFR-mutated lung cancer." (PMID 34112110, 2021). "Chinese patients with lung cancer harbored unique and dispersive EGFR germline mutations and showed unique clinical and genetic characteristics, with varied response patterns to EGFR-TKI treatment." (PMID 34869019, 2021).
lung cancer (continued). "Effective front-line treatment strategies, such as the “primary double-strike therapy” we proposed in our previous review, for patients with EGFR-mutated lung cancers are therefore urgently required." (PMID 34202566, 2021). "In contrast, in EGFR-mutated lung cancer cell lines expressing low levels of AXL (HCC827, HCC4006, and H3255 cells), EGFR TKI tolerance was mediated by an insulin-like growth factor-1 receptor (IGF-1R) through the induction of its transcription factor FOXA1." (PMID 34202566, 2021). "Sixty-three patients who received EGFR-TKIs as first-line therapy for lung cancer, and among whom 35 harbored a sensitizing EGFR mutation were included." (PMID 34680533, 2021). "We evaluated the EGFR mutation status for the treatment of lung cancer according to the results of approved CDx tests to prescribe EGFR‐TKIs." (PMID 33528892, 2021). "Targeting epidermal growth-factor receptor (EGFR) mutations in non-small cell lung cancer revealed genetic heterogeneity in different lung cancer cell lines." (PMID 34367346, 2021). "Among the lung cancer patients who were tested for EGFR gene mutations, the mutation rate in the younger group was higher than that in the older group, but the difference between the two groups was not significant (49.10% vs 44.81%, P = 0.284)." (PMID 33767239, 2021). "Specifically, in EGFR-mutated lung cancer cell lines expressing high levels of AXL (PC9 and HCC4011 cells), a small population of tumor cells tolerant to osimertinib emerged as persisters by restoring the survival signal generated by AXL." (PMID 34202566, 2021). "An important feature in patients with EGFR-mutated lung cancer and MET amplification is that they are resistant to osimertinib." (PMID 34298655, 2021). "In the present study, we found that PHLPP expression level positively correlated with EGFR-TKI sensitivity in EGFR mutation lung cancer." (PMID 34168988, 2021). "For every patient who has lung cancer sheltering a targetable mutation in ALk or EGFR, there are four who lack any targetable mutation." (PMID 34737964, 2021). "Plasma can be collected with minimal invasion from lung cancer patients to detect EGFR mutations in cfDNA." (PMID 33757469, 2021). "Targeted molecular therapy has been successfully applied in several tumors, including ER(+) and HER2(+) breast cancer and epidermal growth factor receptor (EGFR)‐mutated lung cancer, thus demonstrating great progress in precision medical treatment." (PMID 33278864, 2021). "Afatinib has shown favorable response rates (RRs) and longer progression free survival (PFS) in lung cancer patients harboring EGFR mutations compared with standard platinum-based chemotherapy." (PMID 33941115, 2021). "A total of 968 biological processes and 31 KEGG pathways were identified with the filter criteria of adjust p-value< 0.05, of which 20 biological processes and 15 KEGG pathways have previously been linked to lung cancer resistance to EGFR-TKIs." (PMID 34868237, 2021). "This study will lead to a deeper understanding of EGFR mutation-induced drug resistance in lung cancer treatments and will promote the design of genotype-determined therapies or drugs." (PMID 34112110, 2021). "Epidermal growth factor receptor (EGFR) mutations occur in a significant number of lung cancer patients." (PMID 34202748, 2021). "In vitro experiments indicated exosomal shuttling of mutated EGFR from lung cancer cells into dendritic cells." (PMID 33207034, 2021). "Erlotinib is highly effective in lung cancer patients with epidermal growth factor receptor (EGFR) mutations." (PMID 33188726, 2021). "EGFR-TKIs remain the mainstay of pharmacotherapy for the treatment of EGFR mutation-positive lung cancer." (PMID 34831415, 2021).
lung cancer (continued). "Examples include PI3K activation by EGFR in lung cancers harboring somatic-activating mutations in EGFR and HER2 mutations in breast cancers with HER2 amplification." (PMID 33572326, 2021). "The STexS PCR method easily separates the various mutations of EGFR compared to the standard PCR, offering a stable and viable method to detect lung cancer in clinical samples such as blood and lung tissue." (PMID 34580382, 2021). "Remarkably, verteporfin effectively caused the death of EGFR‐TKI‐resistant lung cancer cells by decreasing the expressions of p62 with oncogenic function, YAP, and its target PD‐L1." (PMID 33486901, 2021). "Savolitinib, a potent, selective MET TKI, plus osimertinib are undergoing trials to determine their effect on EGFR mutation-positive lung cancers with MET amplification." (PMID 34677235, 2021). "Using ddPCR and western blots, EVs isolated from lung cancer patient plasma were analyzed for EGFR mutations." (PMID 34692681, 2021). "Mutation of the EGFR gene in exon E21 was significantly associated with gender, lung cancer stage, and treatment method." (PMID 34217313, 2021). "Osimertinib-resistant H1975 stable lung cancer cells with the C797S mutation (H1975 C797S) were established using a retroviral transduction of the EGFR gene with L858R and C797S mutations." (PMID 34439260, 2021). "Various TKIs have been developed to target specific mutations for the treatment of lung cancers, the main molecular cause of which is mutation in the tyrosine kinase domain of EGFR." (PMID 34830169, 2021). "miRNA-dependent EGFR expression and/or hyperactivation have been associated with lung cancer cell behavior, including cell survival, resisting cell apoptosis, cell migration and invasion, proliferative activity, and modulating cell sensitivity to TKIs." (PMID 34830377, 2021). "In another study, the sensitivity and specificity of BALF EV-based EGFR genotyping were high and showed an even better mutation detection rate than tissue- or cytology-based typing of patients with lung cancer." (PMID 34359729, 2021). "Next we examined the effect of combining TNF and EGFR inhibition in lung cancer cell lines with EGFR activating mutations." (PMID 34853306, 2021). "Consistent with previous studies, EGFR was the most commonly mutated gene in early stage lung cancer." (PMID 34109114, 2021). "A number of new targeted therapies have been developed for lung cancers with mutations in specific genes, such as epidermal growth factor receptor (EGFR), which is known to control cell growth and proliferation." (PMID 33188726, 2021). "The United States Food and Drug Association recently approved the 3rd generation EGFR-TKI osimertinib as an adjuvant treatment for use following the resection of EGFR-mutated lung cancer." (PMID 34298845, 2021). "EGFR mutation in lung cancer is a well-known oncogene that impairs response to immunotherapy, which is attributed to an uninflamed phenotype and weak immunotherapy." (PMID 33874915, 2021). "In our study, the knockdown of ANXA1 also increased chemosensitivity to Osimertinib in T790M positive lung cancer cells expression stably expressing L858R + C797S EGFR mutations (H1975C797S)." (PMID 34439260, 2021). "Epidermal growth factor receptor (EGFR) tyrosine kinase inhibitors (TKIs) are the standard treatment for patients with non‐small cell lung cancer (NSCLC) harboring EGFR mutations." (PMID 33533191, 2021). "The evidence for PLEK2 in metastasis is just emerging and closely linked with TGFβ signalling in lung cancer and EGFR signalling in bladder cancer." (PMID 34592589, 2021). "Epidermal growth factor receptor (EGFR) tyrosine kinase inhibitors (TKIs) have been demonstrated to show efficacy in non‐small cell lung cancer (NSCLC) patients with sensitizing EGFR mutations." (PMID 33131198, 2021).